TGFB1 (transforming growth factor beta 1)
Diseases named in the same sentence as TGFB1 in open-access papers (continued):
Sharing a sentence is not in itself a finding about the gene and the disease.
tumor (continued). "Specific inhibition of CXCL12 and TGFβ1 in CAFs inhibited the proliferating tumor cells in the emboli highlighting the importance of CAFs in protecting tumor cells in the emboli." (PMID 33414786, 2020). "It acts with TGFβ1 as a tumour suppressor to regulate pancreatic cell cycle arrest, and apoptosis, mediated by targets such as p21, which causes G1 cell cycle arrest." (PMID 32423157, 2020). "Accumulating studies have indicated that TGFβ1 expression within the tumor microenvironment is frequently enhanced in NSCLC." (PMID 32554855, 2020). "Transforming growth factor beta 1 (TGF-β1), secreted by stromal and tumor cells, is the main factor promoting the mobilization of resident fibroblasts and their activation into CAFs." (PMID 33114328, 2020). "In fact, exposure of tumor constructs to TGFβ1 further stimulated ECM restructuring, creating highly bundled collagen fibers and resulting in stiffer matrices (manuscript in preparation)." (PMID 32555362, 2020). "In the late stage of tumor progression (day 28), there was a reduction in the levels of Csf1, Mmp14, Nedd9, Nf2, Plaur, and Tgfb1 genes by all the investigated compounds." (PMID 32887237, 2020). "Collectively, these observations prompted us to postulate for RAC1B a role as gatekeeper of the epithelial phenotype, an inhibitor of mesenchymal transdifferentiation as well as a genuine tumor suppressor with respect to TGFβ1-driven oncogenesis." (PMID 33266416, 2020). "Pleiotropic effects of TGFβ1 are also observed in cancer systems, where TGFβ signaling can suppress or promote tumor initiation and progression." (PMID 33023180, 2020). "A large body of evidence indicates that TGFβ1 is an important cytokine that promotes tumor progression, as it induces EMT and activates the WNT pathway." (PMID 32018226, 2020). "Given the current concept of autocrine TGFβ as a driver of tumor progression, our observation of RAC1B promoting the expression and secretion of TGFβ1 initially appeared ad odds with its proposed role as a tumor suppressor." (PMID 33260366, 2020). "MSCs transfected with suicide genes and carrying biologically active anti‐tumour substances reach the TME via recruitment by chemotactic signals such VEGF and TGFβ1 secreted by tumour cells and CAFs." (PMID 32588948, 2020). "Conversely, the production of TGFβ1 and periostin by tip cells of the sprouting neovasculature can promote tumor outgrowth." (PMID 33014869, 2020). "Rigorously sticking to this concept allowed us to verify a hitherto unappreciated anti-migratory function for SMAD3 and autocrine TGFβ1, two factors that had before been considered classical tumor promoters." (PMID 33266416, 2020). "This suppressive state was inactivated in sprouting neo-vasculature by endothelial-derived tumor-promoting factors such as TGFβ1 and periostin." (PMID 32014047, 2020). "Higher expression of fatty acid synthase (FASN) in cisplatin-resistant tumor cells signals the downstream molecule TGFβ1, resulting in elevated PD-L1 expression that suppresses NK cell functions." (PMID 33262947, 2020). "TGFβ1 stimulates tumor cell EMT, and promotes cell motility and metastasis via the activation of its down-streaming signaling pathways, subsequently favoring the expression of several transcriptional factors such as MMP2s, α-SMA and Fibronectin." (PMID 32554855, 2020). "We found an increase of TGFB1 mRNA in tumor tissues relative to healthy ones (left), and an increase of TGFB1 mRNA was inversely correlated with a decrease of TGFBR3 mRNA levels in the same patients (right)." (PMID 32471132, 2020). "SMAD-3, which acts downstream of TGFβ1 signaling, directly induces PD-1 expression in adoptively transferred tumor antigen-specific CD8+ T cells isolated from the TME." (PMID 32849557, 2020). "Among them, TGFB1 was the most significantly downregulated gene in both cell lines, which is known to promote the progression of advanced neoplasia." (PMID 32784836, 2020).
tumor (continued). "In a Lewis lung carcinoma spontaneous metastatic mouse model, P2Y12 deficiency reduced pulmonary metastasis and reduced the ability of platelets to secrete active TGFβ1, thus limiting epithelial to mesenchymal transition and invasiveness of tumor cells." (PMID 32092903, 2020). "Apart from TGFβ1, this process is achieved by cancer-related secretion of a range of other pro-inflammatory and tumor promoting factors." (PMID 33023180, 2020). "TGFβ1, a target of the endometrial RAS, was closely associated with RAS component expression and was upregulated in tumor tissues (P = 0.001)." (PMID 32143717, 2020). "In human gastric cancer, tumor infiltrating monoctyes/macrophages can reduce IFNγ, TNFα, and Ki-67 expression of NK cells via TGFβ1, thus impairing NK cell function." (PMID 32762681, 2020). "The fibroblast differentiation is tightly regulated by transforming growth factor-beta 1 (TGF-β1) which is a prominent cytokine found in the tumor microenvironment and during tissue repair processes." (PMID 33008082, 2020). "Prompted by the surprising observation of RAC1B promoting TGFβ1 secretion we set out to study in more detail how endogenous TGFβ1 impacts cell motility in highly invasive tumor cells." (PMID 33260366, 2020). "These investigators reported on the key role played by the cytokine, transforming growth factor β1 (TGFβ1), present at high concentrations in highly immunosuppressive TMEs, in promoting the transition of the anti-tumor N1 TANs to pro-tumorigenic N2 TANs." (PMID 32244751, 2020). "TGFB1 has been reported to exert a tumor inhibiting function in early stages of cervical carcinogenesis, while it plays an oncogenic role at a later stage by promotion of EMT and metastasis, induction of angiogenesis, and escape from immune surveillance." (PMID 32188026, 2020). "At the tumor microenvironment, high levels of transforming growth factor beta 1 (TGF-β1) activate fibroblasts to express 5-lipoxygenase (LOX), responsible for focal adhesion through collagen cross-linking and cell migration via PI3K upregulation." (PMID 32296574, 2020). "According to these studies, the TGFβ1/Smad signalling pathway plays a significant role in tumour development." (PMID 31856384, 2020). "On the other hand, TGF-β concentration in plasma of young mice was increased after treatment with vitamin D compounds in the late stage of tumor progression; similarly, the level of Tgfb1 mRNA in lung tissue increased in these mice (late-stage)." (PMID 32887237, 2020). "To understand the mechanism of CUDC-907 in regulating TGFβ-induced tumor fibrosis, we evaluated PI3K/AKT signaling protein levels of TGFβ1-stimulated CAF1 treated with CUDC-907." (PMID 32943605, 2020). "TGFB1 has previously been shown to act as tumor suppressor during early stages of cervical carcinogenesis, although it takes on a tumor promoting function at a later stage." (PMID 32188026, 2020). "During tumor progression, fibroblasts are transformed into activated fibroblasts called CAFs thanks to Transforming Growth Factor β1 (TGFβ1), Wnt7a, and other factors secreted by the tumor cells." (PMID 33322132, 2020). "TGFB1 acts as an oncogene in tumour progression by inducing cell invasion, dissemination to distant sites and augmenting angiogenesis." (PMID 31679074, 2020). "In another report, treatment of Huh28 and RBE CCA cell lines with the 3-hydroxy-3-methylglutaryl-coenzyme-CoA (HMG-CoA) reductase inhibitor, lovastatin, resulted in reduced TGFβ1 expression as well as reduced tumor cell proliferation and migration." (PMID 31450767, 2019). "DCs dampen inflammation initially in UVB-damaged murine skin through phagocytosis of apoptotic keratinocytes, but they subsequently promote tumor progression in an IL-22- and TGFβ1-dependent manner." (PMID 31022866, 2019). "We have also elucidatedthe role of hsa-miR-4756-3p in tumour cell function in vivoas well as in vitro, which is related with TGFβ1 and forkhead box protein M1 (FOXM1)." (PMID 31554904, 2019).
tumor (continued). "TGFβ1 is a well-known family involved in various tumor processes, such as induction of epithelial–mesenchymal transition and the regulation of cancer migration and invasion (Xu, Lamouille & Derynck, 2009)." (PMID 31293831, 2019). "A possible explanation for the dampened cytotoxicity of NK cells in the tumor microenvironment is the influence of granulocyte colony-stimulating factor (G-CSF) and transforming growth factor beta 1 (TGF-β1)." (PMID 31781671, 2019). "THBS1 has high connectivity in the invasive compartment of P3 tumours with collagens, TGFB1 and integrins." (PMID 30850588, 2019). "Several studies showed that the EMT mediated by TGFβ-1 plays a key role in tumor progression, drug resistance and metastasis." (PMID 31344049, 2019). "Among most upregulated genes in classical tumours, Nt5e, Tgfb1, and Arg1 have been consistently associated to T cell disfunction." (PMID 31439856, 2019). "Tumor exosomes containing TGFβ1 skew immune response away from cytotoxic mechanisms towards regulatory T cell response thereby contributing to tumor immune evasion." (PMID 31137607, 2019). "The experimental results confirmed that the PDGF and TGFβ-1 secreted by platelets can significantly promote the metastasis of tumor cells." (PMID 31208371, 2019). "In a recent study of mice whereby the GARP protein was selectively deleted from platelets, the amount of circulating active TGFβ1 reduced significantly and the tumour growth rate was reduced, corresponding with an increased immune infiltrate into the TME." (PMID 31438626, 2019). "The transforming growth factor TGFB1 (cell development signaling) is normally expressed and secreted by thyroid cells and shows a dual role in tumorigenesis, acting as a tumor suppressor in the early-stage of PTC." (PMID 31126066, 2019). "And the remodeling of tumor interstitial microenvironment was shown by the expression of TGFβ1, epidermal growth factor (EGF), fibroblast activation protein alpha (FAPa), matrix metalloprotein 9 (MMP9)." (PMID 31528217, 2019). "This was a surprising finding because SMAD4 has been identified as a tumour-suppressor gene, but TGFβ1 signalling is the main effector in pulmonary fibrosis." (PMID 30704051, 2019). "It has also been shown that platelets are a crucial source of bioavailable TGFB1 for tumor cells in the vasculature and for support of tumor cell extravasation." (PMID 31215484, 2019). "As hsa-miR-4756-3p widely takes part in cell functions such as invasion, migration and proliferation, and TGFβ-1 signal is an important pathway in tumour development." (PMID 31554904, 2019). "Tgfβ1-C33S crossed with Rag2−/− chimeric mice exhibited reduced inflammation and tumors, implying that TGF-β1-mediated immune responses can suppress tumor development." (PMID 31141984, 2019). "STAT3 knockdown resulted in the reduction of OSCC tumorigenesis/stemness (decrease in the OSCC tumor sphere formation) and oncogenic exosomal cargo contents such as β-catenin, TGFβ1 and miR-21-5p." (PMID 31878245, 2019). "Deregulation of selected genes (Arg1, C7, Lcn2, Nt5e, and Tgfb1) from preinvasive lesion to overt cancers (classical tumours and PDC) was orthogonally confirmed by qPCR." (PMID 31439856, 2019). "In a rat model of iCCA, increased tumor size and enhanced intrahepatic metastasis were detected upon overexpression of TGFβ1." (PMID 31450767, 2019). "In the early stages of tumorigenesis, TGFβ-1 acts as a tumor suppressor, whereas in the later stages this factor assumes a function of tumor promoter." (PMID 31344049, 2019).
tumor (continued). "TGFβ1 behaves as a tumor promoter in late-stage tumorigenesis by increasing angiogenesis, metastasis, and epithelial-mesenchymal-transition (EMT), therefore, the downregulation of TGFβ1 led to the inhibition of cancer cell proliferation." (PMID 30959836, 2019). "Cancer cells undergo EMT in response to TGFβ1, therefore, inhibition of the TGFβ/SMADs pathway suggests that the effect of pioglitazone on tumor cells interferes with EMT process and distant metastasis spread." (PMID 31027492, 2019). "And it is believed that TGFβ1 switches its suppressive role in normal cells into tumor-stimulatory role in cancer cells." (PMID 30250403, 2018). "Tumor-derived exosomes can accelerate angiogenesis and tumor growth in a TGFβ1 (transforming growth factor β1)-dependent pathway to stimulate fibroblasts to differentiate into tumor-promoting stromal myofibroblasts." (PMID 30217217, 2018). "Regulatory T-cells thrive in the cancerous microenvironment, producing excess TGFβ1, preventing the proliferation of other immune cells reducing immune responses to tumors, as well as enhancing tumor cell proliferation." (PMID 30364248, 2018). "TGFβ1 and TNFα are pleiotropic cytokines, which can have both tumor promoting and tumor suppressive effects depending on the context." (PMID 29682184, 2018). "Here, we highlight the role of TGFβ1 as inducer of tumor cell migration by increasing HGF/MET signaling in vitro." (PMID 30004628, 2018). "This inefficient cellular profile was accompanied by high expression of the anti-inflammatory cytokines IL10 and TGFβ1, which is compatible with the “N2-like” neutrophil phenotype previously reported in the tumor microenvironment." (PMID 30233581, 2018). "Tumor tissue was processed to obtain single-cell suspensions for flow cytometry analyses Levels of TGFβ-1 in mouse tumor tissue homogenates and IFNγ in mouse plasma samples were measured by commercial ELISAs." (PMID 30400822, 2018). "The fact that Tgfb1 increased in Robo2F/F epithelial cells was further confirmed by ROBO2 knockdown using siRNA in Panc1 cells—chosen because it is an epithelial tumour cell line that retains some ROBO2 expression." (PMID 30504844, 2018). "It interacts with TSP-1 and then with Transforming growth factor beta 1 (TGF-β1) to promote tumor angiogenesis." (PMID 29914089, 2018). "In this context, TGFβ1 appears as a central player in the tumor microenvironment orchestrating diverse pro-tumoral, anti-inflammatory, and immunomodulatory actions, including the induction and maintenance of an N2 phenotype." (PMID 30233581, 2018). "Evaluation of TGFβ1 receptor transcript levels showed significantly reduced TGFβR2 expression, which probably hamper tumor suppressive effect of TGFβ1 in CML patients." (PMID 29951173, 2018). "To investigate the relevance in vivo, we quantified the expressionof TGFβ1 and stemness-related genes followingtreatment with galunisertib in ex vivo tumor samples from 24 HCC patients." (PMID 29515105, 2018). "In the tumor progression, transforming growth factor β1 (TGFβ1) plays a critical role in tumorigenesis as well as metastasis." (PMID 29995950, 2018). "Total RNA was extracted from paired tumor, normal mucosa and distant metastasis samples and was used for quantitative detection of TGFB1 mRNA by TaqMan qPCR.We observed that TGF-β1 serum levels depend on the -509C/T genotype in combination with gender." (PMID 30071009, 2018). "Altogether, these data demonstrate that TGFβ1 modulates the expression levels of C‐ets‐1 and miR‐128‐3p, thereby triggering promigratory stimuli from the tumor microenvironment in breast epithelial and cancer cells." (PMID 30004628, 2018). "HIF-1α significantly increased the expression of programmed cell death ligand 1 (PD-L1) and the secretion of IL-6, IL-10, and TGFβ1 in MDSCs in tumor bearing mice." (PMID 29682521, 2018).
tumor (continued). "We show here that in many human tumor types, especially those for which checkpoint inhibitors are approved as therapies, TGFβ1 is the predominant isoform." (PMID 30400822, 2018). "We further show that galunisertib treatment inhibits TGFβ1-driven EMT and migration of tumor cells, reverses TGFβ1-mediated immune suppression, and inhibits in vivo growth of human tumor xenografts and syngenic murine tumors." (PMID 29467918, 2018). "This is because the tumor environment is rich in both TGFβ-1 producing cells and in factors that induce TGFβ activation, such as acidic pH, reactive oxygen species, proteases and specific members of integrin family." (PMID 30364222, 2018). "Our data show that combining ephrin-B2-EphB4 inhibitor with RT significantly reduces regulatory T-cell and neutrophil infiltration, TGFβ1 secretion, and stromal fibrosis, enhancing effector T-cell activation and decreasing tumor growth." (PMID 30400822, 2018). "In contrast, in later stages of PDAC when TGFβ1 levels are high in tumours, this scenario will change dramatically." (PMID 30366420, 2018). "Although TGFβ pathway exhibits a tumor-suppressive role, increased level of TGFβ1 in plasma of patients with CRC was associated with the development of metastasis." (PMID 29504907, 2018). "Human OSA patients with high levels of TGFβ3 in tumour tissue have a shorter disease-free survival, whereas human patients with high grade OSA had significantly greater tumour expression of TGFβ1 when compared to low-grade OSA patients." (PMID 30477496, 2018). "Lower transcript levels of TGFβR2 can be the possible reason of decreased signaling activity that abolishes the tumor suppressor effect of the increased TGFB1 levels." (PMID 29951173, 2018). "A major obstacle in this regard is that the tumor micro-environment is enriched with several immunosuppressive cytokines, one of which is transforming growth factor beta 1 (TGF-beta)." (PMID 29342200, 2018). "We also evaluated the relationship between this polymorphism and TGF-β1 serum levels in healthy and patient groups as well as TGFB1 expression in tumor tissues." (PMID 30071009, 2018). "We demonstrate that M7824 reduces plasma TGFβ1, binds to PD-L1 in the tumor, and decreases TGFβ-induced signaling in the tumor microenvironment in mice." (PMID 29721396, 2018). "TGFβ1 expression in invasive cancer correlates with markers of tumor progression, such as metastasis, ECM deposition, and the infiltration of immune suppressive cells." (PMID 29795373, 2018). "This is in contrast to other studies showing that blocking TGFβ1 and TGFβ2 alone was sufficient to improve anti-tumor efficacy in murine tumor models." (PMID 29721396, 2018). "TGFβ1-producing myeloid-derived suppressor cells (MDSCs) have also been reported at high levels in the tumor microenvironment." (PMID 29866156, 2018). "The results from the relative mRNA quantification showed a significant upregulation of TGFB1 in distant metastases compared to primary tumor tissues and higher TGFB1 mRNA levels in men (RQ = 4.959; p = 0.022)." (PMID 30071009, 2018). "It is known to alter the function of TGFβ1 in endothelial cells and plays an important role in angiogenesis, fetal development, wound healing, and tumor metastasis." (PMID 29944724, 2018). "Treatment of 4T1-pSMAD-luc tumor cells with M7824 either prior to or after the addition of TGFβ1 reduced TGFβ1-dependent phosphorylation of SMAD2, as indicated by decreased SMAD2 promoter-dependent luciferase activity." (PMID 29721396, 2018). "Adding to this complication, TGFβ-1 is also known to show dual properties and can both induce and inhibit tumor dormancy in a context-dependent manner." (PMID 30603045, 2018). "Cancer cell-derived exosomes are able to stimulate fibroblast differentiation into tumour-promoting stromal myofibroblasts through a TGFβ1-dependent pathway, accelerating angiogenesis and tumor growth." (PMID 29246022, 2017).